RSRC2 (arginine and serine rich coiled-coil 2)
Synonyms: FLJ11021
Tractability: PROTAC: UniProt records ubiquitination sites on it; ubiquitination databases record sites on it; its protein half-life has been measured.
Gene: Protein-coding gene on chromosome 12 (122,503,454 to 122,527,100, reverse strand). Ensembl gene ENSG00000111011.
Subcellular location (Human Protein Atlas): Nuclear speckles; Cytosol; Nucleoli fibrillar center
Gene Ontology:
Molecular function: protein binding; RNA binding
Genetic constraint (gnomAD): Loss-of-function variants: 2 observed, 46.61 expected, observed/expected ratio (o/e) 0.0429, 90% interval 0.017 to 0.14. The upper end of that interval is the gene's LOEUF score, 0.14, which puts it in group 1 of 6, group 1 being the genes least tolerant of losing a copy. Missense variants: 344 observed, 473.47 expected, observed/expected ratio (o/e) 0.73, 90% interval 0.66 to 0.79. Synonymous variants: 178 observed, 155.63 expected, observed/expected ratio (o/e) 1.14, 90% interval 1.01 to 1.29.
Homologues: Orthologues: macaque RSRC2 (99% identical), chimpanzee RSRC2 (99% identical), dog RSRC2 (99% identical), pig RSRC2 (99% identical), rabbit RSRC2 (98% identical), guinea pig RSRC2 (98% identical), mouse Rsrc2 (96% identical), rat Rsrc2 (96% identical), tropical clawed frog rsrc2 (71% identical), zebrafish rsrc2 (65% identical). Paralogues in human: SRSF4 (19% identical), SRSF6 (18% identical), SRSF5 (14% identical), RSRP1 (13% identical), SRSF7 (13% identical), SRSF1 (12% identical), SRSF3 (11% identical), SRSF9 (9% identical).
Diseases named in the same sentence as RSRC2 in open-access papers:
RSRC2 is named in the same sentence as 21 diseases in open-access papers, as found by Europe PMC text mining. Sharing a sentence is not in itself a finding about the gene and the disease. The quoted sentences say what the papers report.
triple-negative breast carcinoma (3 papers, 2020 to 2023). An invasive breast carcinoma which is negative for expression of estrogen receptor (ER), progesterone receptor (PR), and human epidermal growth factor receptor 2 (HER2). "SCIN was identified as a novel transcriptional target of RSRC2 in triple-negative breast cancer cells." (PMID 38201443, 2023). "TRA2A can reduce the level of normal RSRC2 splicing product RSRC2s and increase the expression of RSRC2l, an abnormal mRNA splicing product of RSRC2, which promotes the progression of triple negative breast cancer." (PMID 35669517, 2022). "Our study found RSRC2 expression was lost in triple-negative breast cancer tissues." (PMID 38201443, 2023). "In two studies, the splicing factors PTBP1 and TRA2A were up-regulated in resistant cells and promoted resistance to gemcitabine in pancreatic cancer through AS regulation of the PKM gene, and to paclitaxel in triple-negative breast cancer through AS of RSRC2, respectively." (PMID 31943118, 2020). "The clarification of relationship between RSRC2 and SCIN provided a new sight for triple-negative breast cancer treatment." (PMID 38201443, 2023).
breast carcinoma (2 papers, 2021 to 2023). "Low expression of RSRC2 was associated with worse prognosis of breast cancer patients." (PMID 38201443, 2023). "The low expression of RSRC2 was associated with a worse prognosis for patients with breast cancer." (PMID 38201443, 2023). "Downregulation of RSRC2 was observed in breast cancer tissues through a large-sample bioinformatics multiple database analysis, especially in TNBC." (PMID 38201443, 2023). "It was also confirmed from the GEPIA database and Xiantao Academic online analysis database that the RSRC2 expression was significantly lower in the breast cancer tissues (n = 1085 and n = 1099) than in the normal tissues (n = 291 and n = 292)." (PMID 38201443, 2023). "Consistently, the bioinformatics analysis showed breast cancer with RSRC2 low expression was prone to drug resistance than with RSRC2 high expression." (PMID 38201443, 2023). "Next, we further demonstrated the correlation between the RSRC2 mRNA levels and the clinical data of breast cancer patients." (PMID 38201443, 2023). "Meanwhile, the RSRC2 expression was significantly lower in breast cancer tissues than in normal tissues." (PMID 38201443, 2023). "RSRC2 low expression can predict poorer overall survival in breast cancer, even in different molecular subtypes, including TNBC." (PMID 38201443, 2023). "Meanwhile, we found that the RSRC2 expression was lower in the chemotherapy non-responder than in the chemotherapy responder by using the Kaplan–Meier Plotter, suggesting that breast cancer with RSRC2 low expression was prone to drug resistance than RSRC2 high expression." (PMID 38201443, 2023). "RSRC2 low expression can predict poorer overall survival (OS) in total breast cancer." (PMID 38201443, 2023). "Importantly, the RSRC2 expression was lowest in TNBC among all the subtypes of breast cancer (p < 0.001)." (PMID 38201443, 2023). "Therefore, the decreased RSRC2 protein expression occurred in the breast cancer tissues compared to the normal breast tissues." (PMID 38201443, 2023).
neuroblastoma (2 papers, 2010 to 2017). Neuroblastoma (NB) is the most common solid, extracranial childhood tumor. "Increased expression of RSRC2 has been observed in neuroblastomas harboring somatic gain of chromosome 12q, and a MIER2-RSRC1 fusion has been observed in prostate cancer." (PMID 28545128, 2017). "Using the in silico data mining approach, we identified elevated expression of five genes located at the 12q24.31 amplicon in neuroblastoma (DIABLO, ZCCHC8, RSRC2, KNTC1 and MPHOSPH9)." (PMID 20444257, 2010). "In addition to DIABLO, also ZCCHC8, RSRC2, KNTC1 and MPHOSPH9 showed statistically increased expression in neuroblastoma samples when compared to the groups of healthy samples." (PMID 20444257, 2010).
Obesity (2 papers, 2017 to 2018). Accumulation of substantial excess body fat. "Instead, our screen suggests that different nearby cis gene may be more fruitful for further functional follow up for obesity, namely ZCCHC8, VPS33A, RSRC2; SPDEF, NUDT3; SETD1, VKORC1; SGSM2, SRR; VASP, SIX5; OTX1; BANK1; ARIH1; ELL; CHST8, respectively." (PMID 29608557, 2018).
esophageal cancer (1 paper, 2023). A primary or metastatic malignant neoplasm involving the esophagus. "The RSRC2 mRNA expression level of esophageal cancer cell lines and resected cancer tissues was significantly lower than that of normal esophageal mucosa." (PMID 38201443, 2023). "RSRC2 expression could inhibit esophageal cancer cell growth and is significantly negatively related to the esophageal cancer infiltration level, spreading to the lymph node and blood vessels." (PMID 38201443, 2023).
glioblastoma (1 paper, 2023). The most malignant astrocytic tumor (WHO grade IV). "On the other hand, the expression level of RSRC2 in glioblastoma (GBM), kidney chromophobe cell carcinoma (KICH), kidney renal clear-cell carcinoma (KIRC), thyroid carcinoma (THCA) and uterus endometrial carcinoma (UCEC) was lower than that in the normal tissues." (PMID 38201443, 2023).
oesophageal cancer (1 paper, 2021). "RSRC2, a tumour suppressor gene, was first found to inhibit oesophageal cancer cell proliferation and affect survival." (PMID 34772375, 2021).
pancreatic ductal carcinoma (1 paper, 2023). "Later research found that the expression level of RSRC2 in pancreatic ductal carcinoma was significantly lower than that in normal pancreatic tissue, and it was negatively correlated with the clinical stage of pancreatic ductal carcinoma." (PMID 38201443, 2023).
cancer (4 papers, 2015 to 2023). A tumor composed of atypical neoplastic, often pleomorphic cells that invade other tissues. "In this study, we used bioinformatics databases to further carry out a large-sample analysis for the role of RSRC2 in cancer." (PMID 38201443, 2023). "We analyzed the expression level of the RSRC2 mRNA in the TCGA database for multiple cancer types." (PMID 38201443, 2023). "A study on colon cancer found that malignant biological behaviors such as the proliferation, migration and invasion of cancer cells were enhanced after SOCS3 downregulation, accompanied by a decrease in the RSRC2 expression level." (PMID 38201443, 2023). "In addition, we found in this list established cancer genes involved in other types of cancer, such as PDE4DIP, SF3B1, AHNAK, COPB2, CSDE1, KIF5B, NDUFA10, RSRC2." (PMID 31949199, 2020).
tumor (4 papers, 2021 to 2024). "Fusion ZCCHC8--RSRC2, previously detected in several tumor studies, was identified as highly prevalent and broadly expressed across cell types in HGSOC Patient-3 tumor and matched normal samples, identified in 46% and 36% of sequenced cells, respectively." (PMID 38464114, 2024). "In summary, our study reveals that RSRC2 acts as a tumor suppressor in TNBC development and progression through negatively regulating SCIN-mediated cell function, thus providing a potential target for TNBC treatment." (PMID 38201443, 2023). "In summary, we demonstrated that RSRC2 served as a tumor suppressor in TNBC through negatively regulating SCIN-mediated cell function." (PMID 38201443, 2023). "The immunohistochemical staining obtained from HPA showed the strong expression of the RSRC2 protein in the normal tissues and the moderate expression of the RSRC2 protein in the tumor tissues." (PMID 38201443, 2023). "RSRC2 was proved to be a tumor inhibitor and a prognostic target gene inESCA." (PMID 34194494, 2021). "Some abnormally regulated genes in our prognostic signature participated in tumour initiation and development, including NUMB, RSRC2, TMC6, CASP8, TRIO, and COMMD5." (PMID 34772375, 2021). "RSRC2 was upregulated in miR-182-silenced colorectal cancer cells, which induced apoptosis, inhibited cell proliferation and invasion and was not conducive to tumor formation in immunodeficient mice." (PMID 38201443, 2023).
RSRC2 also shares sentences with these, for which no sentence is quoted: pancreatic cancer (2 papers); cholangiocarcinoma (1); colon adenocarcinoma (1); Ewing sarcoma (1); head and neck squamous cell carcinoma (1); kidney chromophobe cell carcinoma (1); lung adenocarcinoma (1); lung squamous cell carcinoma (1); prostate carcinoma (1); stomach adenocarcinoma (1); thyroid carcinoma (1).